STAT3 (signal transducer and activator of transcription 3)
Diseases named in the same sentence as STAT3 in open-access papers (continued):
Sharing a sentence is not in itself a finding about the gene and the disease.
tumor (continued). "A lot of evidences suggest that SOCS5 serves as a tumor suppressor in cancers by negatively regulating JAK2/STAT3." (PMID 33935775, 2021). "The phosphorylation level of STAT3 was decreased, the antiapoptotic signal was weakened, and the growth of xenograft of HepG2 tumor was significantly inhibited." (PMID 34539403, 2021). "The anti-inflammatory cytokine, IL-10 can paradoxically induce STAT-3 activation, which also leads to induction of tumor cell proliferation." (PMID 34307156, 2021). "STAT3 inhibition in tumor cells increases the expression of cytokines and chemokines that ameliorate the TME, including DCs and tumor-specific T cells response." (PMID 33957948, 2021). "MiR-124 through various cascade pathways, including the PTB1/PKM1/PKM2 pathway, or by targeting the STAT-3 molecule inhibits CRC tumor growth." (PMID 33987190, 2021). "Circulating M-MDSCs maintain high levels of STAT3 signaling until they reach the site of the tumor, where hypoxia induces a rapid downregulation of STAT3 resulting in differentiation into TAMs." (PMID 33800156, 2021). "The activation of IL-6/JAK2/STAT3 signaling pathway plays an active role in tumor growth and progression." (PMID 34881181, 2021). "It is generally considered that STAT3 is activated by cytokines and growth factors produced within the tumour microenvironment." (PMID 33410581, 2021). "We further show that BRD4 phosphorylation promotes interaction with STAT3 to induce chromatin remodeling through concurrent binding to enhancers and super-enhancers, supporting a tumor-promoting transcriptional program." (PMID 34290255, 2021). "As it has previously been shown that activated MET induces tumor invasion via phosphorylation of STAT3, we assessed levels of phospho-STAT3 (p-STAT3) and found decreased p-STAT3 after the introduction of miR-34a-5p mimic in CAL27 cell lines." (PMID 33596979, 2021). "IL-6, produced by tumors or tumor-infiltrating cells, binds to its target receptor IL-6R and leads to Jak2/STAT3 activation." (PMID 34833950, 2021). "Given the importance of STAT3 in tumor growth, survival, and chemoresistance, several clinical trials have been carried out with STAT3 inhibitors." (PMID 34120146, 2021). "STAT3 phosphorylation is conducive to malignancy by upregulating the expression of pro-oncogenes, such as survivin, allowing tumor cells to survive and proliferate." (PMID 33758275, 2021). "These suggest an unreported role of STAT3 in regulating V-ATPase expression in anchorage-independent cells - a precondition for metastasizing tumor cells." (PMID 34234852, 2021). "Treatment of A549 NSCLC cancer cells with small molecule SRC kinase inhibitors (e.g., PD180970 and SU6656) induced cell cycle arrest and tumor cell apoptosis by suppressing STAT3 activity." (PMID 34944848, 2021). "The activation of STAT3 in OS by IL-6 is an important mechanism in OS tumor progression and metastasis." (PMID 34681692, 2021). "All these markers except sIL-6Rα, OCLN, STAT1 and STAT3, are upregulated in tumor samples compared to controls." (PMID 33846436, 2021). "Suppressor of cytokine signaling (SOCS) 3, an inhibitor of the JAK/STAT3 signaling pathway, is correlated to the pathogenesis and progression of multiple cancers and regarded as a crucial tumor suppressor." (PMID 34330232, 2021). "In the tumor microenvironment, hyperactivation of IL-6/JAK/STAT3 signaling pathway acts as a powerful suppressor of anti-tumor immune response and as a promotor of tumor progression, leading to a poor prognosis of cancer patients." (PMID 33854592, 2021). "The JAK2/STAT3 signaling pathway has been widely demonstrated to be involved in tumor growth and chemoresistance in various malignancies." (PMID 34496932, 2021). "A previous study reported that HSP90 is involved in activating the IL6/JAK/STAT3 signaling pathway to affect tumor progression." (PMID 34712697, 2021).
tumor (continued). "In an MDA-MB-231-DTR-bearing xenograft mouse model, the combination of pulvomycin and docetaxel effectively inhibited tumor growth through STAT3 regulation." (PMID 33920736, 2021). "ICAMs, through the activation of STAT-3, lead to increased tumour growth, angiogenesis, EMT, and an immunosuppressive TME." (PMID 34439879, 2021). "STAT3 mediates key inflammatory mechanisms in colitis-associated cancer, becomes excessively activated in CRC, and enhances cancer cell proliferation, tumor growth, angiogenesis, invasion, and migration." (PMID 34440220, 2021). "As for evidence in BC, the inhibitors G-quartet and S3I-201 have been shown to block STAT3′s ability to bind to DNA both in vitro and in vivo, with evidence of tumour regression in BC xenograft models." (PMID 34834425, 2021). "Persistent hyperactivation of the IL-6/STAT3 signalling pathway also leads to angiogenesis, epithelial-mesenchymal transition and stemness in the tumour microenvironment." (PMID 34078370, 2021). "A xenograft model confirmed the ability of OV treatment to counteract tumor growth by inhibiting IL-6, STAT3, β-catenin, and exosomal miR-1246 in mice serum." (PMID 34638913, 2021). "Despite the extensive function of STAT3 among several cancer cells, growing evidence has disclosed the contribution of activated STAT3 to cancer cell proliferation and aberrantly activated STAT3 is related to tumor malignancy." (PMID 34513945, 2021). "Constitutive activation of STAT3 is usually observed and is closely related to tumor cell proliferation, invasion, metastasis, and angiogenesis." (PMID 34306165, 2021). "The tumour microenvironment promotes tumour angiogenesis by activating STAT3 in vascular endothelial cells, and bufalin can precisely inhibit angiogenesis by targeting STAT3." (PMID 34496870, 2021). "STAT3 activation in tumor cells also represses the expression of NK cell-chemotactic factors, which reduce the migration of NK cells in the TME." (PMID 34025641, 2021). "It has been reported that IL‐23 can mediate inflammatory processes, providing a tumor microenvironment by activating the signal transducer and activator of transcription 3 (STAT3) signaling pathway in tumors." (PMID 34129726, 2021). "Leptin often plays a tumor-promoting effect through the STAT3 signaling pathway and stimulates cell proliferation, migration and invasion." (PMID 34485124, 2021). "TLR initiate a cascade that begins with activation of canonical (classical) NF-kB and ERK MAPK pathways, amplified by induced host mediators, with subsequent enrollment of STAT3 activities, which affects essentially all cell types present in the tumor." (PMID 35048056, 2021). "Overall, these data show that inhibiting tumor-NLRP3 alone is sufficient to reduce IL-6/STAT3 activation, resulting in the reduction of immunosuppressive gene expression in PMN-MDSCs." (PMID 34531850, 2021). "TKI258, another VEGFRs and PDGFRs inhibitor, reduces p-AKT and p-STAT3 levels in tumor xenograft nude mice." (PMID 34122447, 2021). "Many STAT3 target genes have been shown to promote inflammation, immune‐escape, tumour invasion and metastasis by up‐regulating cytokines, such as IL‐6, making STAT3 a target of interest in cancer therapy." (PMID 33274592, 2021). "Downregulation of PD-L1 and STAT3, inhibit proliferation, migration and angiogenesis of cancer cells, inhibit tumor growth in the body." (PMID 34616746, 2021). "It is well documented that STAT3 signaling plays an important role in tumor–immune cell interaction, cancer progression, metastasis, cell proliferation and immune escape." (PMID 34440920, 2021).
tumor (continued). "Although IL-20 subfamily cytokines have been extensively reported to activate STAT3 to exhibit oncogenic effects, STAT3 has also been shown to be able to switch its roles from tumor-promoting at early stages to tumor-suppressing in the invasion process." (PMID 34114949, 2021). "Further investigation into the mechanism demonstrated that ESR1 acts as a tumor suppressor by inhibiting the JAK/STAT3 signaling pathway." (PMID 33865377, 2021). "The canonical inducer of STAT3 activation is IL-6, which is also a master regulator of inflammation and tumor growth." (PMID 33917315, 2021). "In IBD, the interleukin (IL)-6/signal transducer and activator of transcription 3 (STAT3) signaling is an important regulator of proliferation of tumor cells." (PMID 33808480, 2021). "The activation of the STAT3 pathway supports tumor angiogenesis, growth, invasion, tumor cell proliferation and survival, in addition to facilitating evasion from the immune surveillance; therefore, this molecule is a promising target for cancer therapy." (PMID 33525658, 2021). "Upregulating miR-181d inhibits GBM cell migration, invasion, and tumour growth in GBM mouse models by suppressing STAT3 or STAT5A expression." (PMID 34425834, 2021). "The transcription factor STAT3 can promote tumor growth and angiogenesis, increase the invasion and migration of tumors, and inhibit immune responses." (PMID 33959183, 2021). "Some of these drugs also demonstrate complementary anti-tumor effects when combined with chemotherapy, tyrosine kinase inhibitors, and immunotherapy, suggesting the additive benefit of co-targeting STAT3 in these settings." (PMID 34944848, 2021). "In summary, the evidence suggests that H2S donors have a dominant anti-cancer effect by reducing tumor volume, weight, growth, and regulating p-STAT-3 levels in a concentration-dependent manner." (PMID 33390834, 2021). "Through conducting functional and mechanistic studies, we identified that KPNA2, a central importin in nuclear import, maintained PD-L1 expression by mediating nuclear translocation of STAT3 and ultimately led to tumor immune evasion." (PMID 33728352, 2021). "Previous studies have shown that STAT3 activation promotes tumour angiogenesis by increasing VEGF expression." (PMID 34496870, 2021). "Despite major efforts, targeting STAT3 in tumor cells has proved challenging likely due to its cytosolic localization and lack of enzymatic activity." (PMID 33986188, 2021). "In many cancer cells, persistent activation of STAT3 pathways can promote tumor cell proliferation, survival, angiogenesis and immune evasion." (PMID 34679649, 2021). "Through its interaction with STAT3, NDUFA13 represses STAT3 dependent transcription and thus has an anti-proliferative pro-apoptotic effect and plays a role in tumor suppression." (PMID 35047558, 2021). "In tumor cells, aberrant activation of the tyrosine kinase pathway leads to excessive and continuous activation of STAT3, which provides further signals for tumor cell growth and surrounding angiogenesis." (PMID 34502195, 2021). "In PC models, STAT3 activity in tumor-infiltrating MDSCs correlated to increased PD-L1 levels and elevated plasma levels of IL6-type cytokines, such as LIF, suggesting a potential cross-talk mechanism promoting tumor immune evasion." (PMID 34945784, 2021). "Taken together, these data suggested that W2014-S significantly suppressed excessive STAT3 signaling as well as tumor growth in mouse models." (PMID 33391507, 2021). "STAT3 signaling is critical for driving tumor growth, migration, angiogenesis, and inflammatory cross-talk with immune cells during the carcinogenesis." (PMID 34404767, 2021). "In vivo depletion experiments also demonstrated that the STAT3 pathway blockade was essential in inhibiting tumor progression, suggesting a potential target therapy." (PMID 33936081, 2021).
tumor (continued). "Signal transducer and activator of transcription 3 (STAT3) plays important roles in tumours through its effects on cell proliferation, apoptosis, survival, angiogenesis, metastasis and immunoregulation." (PMID 33259114, 2021). "Persistent activation of STAT3 due to phosphorylation of Tyr705 has been observed in nearly 30–100% of human tumor specimens." (PMID 33420372, 2021). "Third, we revisit the transcription factor STAT3 as a central tumor-cell intrinsic and microenvironmental target of silibinin in primary lung tumors and brain metastasis." (PMID 34208282, 2021). "IL-17 induces the production of IL-6 by stromal and tumor cells, thus activating the STAT3 pathway, which favors the expression of inflammatory factors important for the regulation of leukocyte infiltration in inflammatory tissues." (PMID 34299314, 2021). "In mouse models of colon carcinoma, IL-27 induced NK cell-mediated cytotoxicity and anti-tumor immunity by activating STAT3 and triggering the expression of perforins." (PMID 33418929, 2021). "STAT3 (Signal transducer and activator of transcription 3) is a critical transcriptional factor identified as a central regulator of tumor metastasis." (PMID 33413536, 2021). "In the tumor microenvironment, IL-6/JAK/STAT3 signaling acts to drive the proliferation, survival, invasiveness, and metastasis of tumor cells, while strongly suppressing the antitumor immune response." (PMID 33540700, 2021). "While cancer cells in contact with tumor stroma in lean patients displayed a weak presence of nuclear p-STAT3." (PMID 34408135, 2021). "Blocking STAT3 activation by a specific inhibitor effectively blocked the tumor spheroid formation and decreased the number of CD44+ ALDH+ cells, and further induced apoptosis in HNSCC, this was consistent with our study." (PMID 34502158, 2021). "We and others have also demonstrated the importance of STAT3 in suppressing antitumor immune responses in both animal tumor models and clinical studies." (PMID 34956861, 2021). "IL-23 signaling in tumor cells is important for the intra-tumoral production of downstream cytokines, which are either direct (IL-6, IL-22) or indirect (IL-17A) STAT3 activators." (PMID 33418996, 2021). "Infiltrated macrophages can release STAT3 to induce PD-L1 expression in GC, which helps tumor cells escape from cytotoxic T-cell killing and promotes the proliferation of tumor cells." (PMID 35096565, 2021). "Another significant angle of recent investigations pertains to the effect of RAS signaling in tumor cells on activation of key pathways such as STAT3 and NF-κB in surrounding intra-tumoral immune cells." (PMID 33917037, 2021). "TAMs directly enhance the tumor-initiating capacity of PCSCs by activating the transcription factor STAT3 in PCSCs, which facilitates macrophage-mediated suppression of CD8 T-cells." (PMID 34201127, 2021). "We previously reported that L-MDSC inhibits CAR-T-dependent tumor cytotoxicity in vitro, which gets reversed by targeting STAT3 that induces apoptosis in L-MDSC." (PMID 34451932, 2021). "Hyperactivation of STAT3 is prevalent in both cancer cells and immune cells of the tumor ecosystem of various origins." (PMID 34885171, 2021). "Given its multifaceted role in NSCLC development, progression, and therapy resistance, STAT3 represents an attractive drug target to impair tumor growth." (PMID 34944848, 2021). "An increase in CD14+HLA-DRlo/neg monocyte population was confirmed in PDAC patients by tumour-derived exosomes that involves an alteration in STAT3 signalling, induction of arginase expression and ROS generation." (PMID 34671031, 2021). "STAT3 signaling controls the expression of genes involved in tumor growth, survival, invasion, and angiogenesis." (PMID 35155571, 2021). "For instance, STAT3 activation acts as a crucial regulator of gliomagenesis by inducing angiogenesis, immunosuppression and tumour invasion." (PMID 34013637, 2021).
tumor (continued). "First, a genetic approach to evaluate the role of STAT3 in fraxetin-mediated anti-tumor effects needs to be presented." (PMID 34320467, 2021). "In summary, STAT3 signaling constitutes a crucial hub through which the tumor microenvironment is shaped and driven toward immunosuppression." (PMID 33498872, 2021). "As well, BC cells can upregulate IL-6 expression in adipocytes, which in turn promotes angiogenesis, tumor cell proliferation and survival via the Janus kinase/signal transducer and activator of transcription 3 (JAK/STAT3) signaling pathway." (PMID 34638283, 2021). "In gastric carcinoma, CAFs induced the upregulation of DDR1 in tumor cells in vitro by potently activating STAT3, increasing its tumorigenic potential." (PMID 33917302, 2021). "The upregulation of cancer-promoting inflammatory cytokines (host and tumor-secreted), such as NF-κB, COX-2, IL-1, IL-6, TNF-α, and IFN-γ, is strongly associated with STAT3 and AKT signaling activation in oral squamous cell carcinoma in vitro." (PMID 34950252, 2021). "Apart from that, IL‐6/STAT3 signaling facilitated tumor development by reducing M1 polarization while increasing M2 differentiation of TAM." (PMID 34566989, 2021). "The results suggested that hepatic inflammatory microenvironment impaired the anti‐tumour effect of sorafenib by cytokines‐induced activation of STAT3." (PMID 33410581, 2021). "IL-6 activates Stat-3 signalling in regulator T cells and helps tumour cells escape immune surveillance." (PMID 34223877, 2021). "Irradiation promotes IL-6 production by the tumor microenvironment, which results in STAT3 phosphorylation and subsequent anti-inflammatory CCL2, CCL4, VEGF, and TGF-β cytokine production." (PMID 33800829, 2021). "Furtherly, the recruited macrophages in turn secret IL-6 to activate JAK2/STAT3 signaling, promoting tumor metastasis." (PMID 34326840, 2021). "STAT3 exerts its function by promoting tumour metastasis through mediating tumour cell proliferation, migration, and invasion as well as tumour angiogenesis." (PMID 34208965, 2021). "Subsequently, we found that combination treatment had a better effect on reducing the phosphorylation of the STAT3/Bcl-2 pathway via western blottings on xenograft tumor tissues." (PMID 34611143, 2021). "STAT3 increases the expression of genes that can facilitate angiogenesis, tumor survival, cell cycle progression and resistance to cell death." (PMID 34199460, 2021). "Some investigations have revealed that a miR-197-mediated CKS1B/STAT3 axis exerts a role in tumor progression, which is regulated by different genes, such as Bcl-2, c-Myc, and cyclin D125." (PMID 34907223, 2021). "Deletion of CREPT led to a decrease, but overexpression of CREPT resulted in an increase, in STAT3-initiated tumour cell proliferation, colony formation and tumour growth." (PMID 33531691, 2021). "STAT3 is a member of the STAT protein family and is significantly associated with promoting tumor development and immunosuppression." (PMID 34745261, 2021). "Although 3FC reduced the nuclear STAT3 and its DNA interaction capability, the inhibition of phosphorylation is crucial in driving tumor cell proliferation and malignant progression." (PMID 35053027, 2021). "In terms of the mechanism responsible for this effect, the 3′-UTR of CASC9 can interact with miR‐519d, which acts as a tumour suppressor by directly targeting the 3′‐UTR of STAT3 mRNA, to increase the expression of STAT3." (PMID 34425834, 2021). "The immunofluorescence results showed that the number of blood vessels in subcutaneous tumours and the proportion of activated STAT3-positive blood vessels in the bufalin group were significantly lower than those in the vehicle group." (PMID 34496870, 2021). "The fact that STAT3 signalling induces the secretion of factors responsible for the formation of the PMN has also been demonstrated in tumour cells and tumour-associated macrophages (TAMs) within the primary tumour microenvironment." (PMID 35006432, 2021).